ATG12 (autophagy related 12)
Diseases named in the same sentence as ATG12 in open-access papers (continued):
Sharing a sentence is not in itself a finding about the gene and the disease.
cancer (continued). "The mutations with mononucleotide repeats have been found in ATG2B, ATG5, ATG9B, and ATG12 genes in gastric and colorectal cancers, which may be involved in cancer development by dysregulating autophagy." (PMID 34443541, 2021). "Similarly, many studies have shown that regulating the expression level of ATG12 can increase tumor cells’ sensitivity to anti-cancer drugs and significantly improve the effectiveness of tumor treatment." (PMID 34636718, 2021). "An increasing number of studies indicated that ATG12 induced autophagy in various human cancers." (PMID 33837652, 2021). "The frameshift mutations with mononucleotide repeats have been found in ATG2B, ATG5, ATG9B and ATG12 genes in gastric cancer and colorectal cancer, which may be involved in cancer development by deregulating the autophagy process." (PMID 31969156, 2020). "Among mammal ATG proteins, Beclin-1, ATG5, ATG7, ATG12, ATG16L1 and LC3B are the most studied with respect to inflammation, and defects in autophagy are linked to many inflammatory diseases and cancer." (PMID 31969156, 2020). "We found that AS-IV upregulated Atg12 and induced cancer cell autophagy through DCP1A and TMSB4X." (PMID 32265995, 2020). "We point out a potentially unique role for Atg7, as neither chemical inhibition with Chloroquine nor loss of Beclin-1 or Atg12 induced cancer cell death, even though autophagy signaling was reliably blocked." (PMID 32046105, 2020). "We then identified and characterized ATG5 splice variants and more than 50 structure-guided and somatic cancer mutations, which revealed that the mutually stabilizing ATG5-ATG16L1 interaction was an essential prerequisite for ATG12 conjugation and ATG12–ATG5-ATG16L1 complex formation." (PMID 31636955, 2019). "ATG12, a vital regulator of autophagy, is upregulated in various cancers." (PMID 29162158, 2017). "Therapeutics that specifically target cancers involving Mcl-1 overexpression may function to improve binding of ATG12 to Mcl-1." (PMID 23840208, 2013). "Importantly, when investigating therelationship between the biological roles of autophagy in trastuzumab-mediated cancer therapy, weconcluded that ATG12-related autophagic flux specifically functions as a protective cellularphenotype against HER-targeting drugs." (PMID 23307622, 2012). "Recent studies have shown that the dysregulation of autophagy-related genes, such as ATG12 and ULK1, plays a crucial role in the progression of various cancers, including gastric cancer, acute myeloid leukemia, renal cell carcinoma, and BC." (PMID 40066127, 2024). "It reported that knockout of ATG12 sensitizes cancer cells to CTLs, whereas knockout of ATG5 or ATG16L1 together with ATG12 results in resistance of cancer cells to CTLs." (PMID 36230955, 2022). "In our study, expression of ATG12 and ATG7 showed up-regulation while ATG10 expression was down regulated in cancer tissues." (PMID 33604190, 2021). "As a connection between PI3K complex, ULK complex and ATG12 system, WIPI2 showed higher expression in cancer tissue." (PMID 33604190, 2021). "Increased expression of the autophagy-related proteins Atg5, Atg7, Atg12, p62, and LC3 enhanced autophagy, which would degrade inadequate protein aggregates and also provide nutrients for rapidly growing cancer cells." (PMID 28358375, 2017). "FOXO3 overexpression correlated with expression of the Gabarapl1, ATG12, PIK3C3, LC3, and Beclin1 genes in cancer tissues." (PMID 24527027, 2014). "Additionally, dysfunctions in ATGs, such as ATG12, ATG14, and ATG5, can affect the autophagy process, thereby influencing the initiation and progression of cancer, as well as response to chemotherapy." (PMID 39664581, 2024).
cancer (continued). "In addition, RTA dh404 promoted or repressed genes related to autophagy in cancer cells, including four genes (SQSTM1(p62), MAP1LC3B(LC3B), ATG5, and ATG12) in GBM8401 cells and two genes (SQSTM1 (p62) and MAP1LC3B (LC3B)) in U87MG cells." (PMID 36835414, 2023). "The genes ITGA3, HSPA8, CTSD, ATG12, CLN3, ATG7, and MAP1LC3C negatively influenced patient survival, whereas WIPI1 may protect the patients from cancer-related death." (PMID 35186475, 2022). "Next, we questioned whether the prognostic value of ATG12 expression was restricted to HNSCC only and mined the TCGA database for additional cancer types." (PMID 34904929, 2022). "Individual miRNAs can regulate multiple target genes; several miR-23b target genes, such as autophagy-related gene 12 (ATG12), chemokine ligand 7 (CCL7), and E-cadherin, have been identified and validated and play significant roles in inflammatory and cancer-related pathways." (PMID 31780861, 2019). "Compared with the other genes, ATG12 and HMGB2 were more related to chemoresistance of cancer." (PMID 25996293, 2015). "In contrast to patient tumors, screening of >20 cancer cell lines, including 8 HNSCC, available in our laboratory indicated that all in vitro cell lines express ATG12 mRNA and protein (not shown)." (PMID 34904929, 2022). "In fact, we found in a previous study that serum deprivation decreases the complexation between survivin and ATG12/ATG5 (possibly to upregulate autophagy), but not caspase-3 (concurrently maintains apoptosis inhibition), in human cancer cells." (PMID 32019552, 2020).
tumor (49 papers, 2012 to 2025). "Similar to what was observed upon deletion of Atg5, loss of Atg12 or Atg9 in ECs increased p62 granularity in CD31+ tumor vessels indicating reduced autophagy flux (Fig EV1D and E)." (PMID 38009521, 2023). "In 14 of the 51 HNSCC tumors with available tissue biopsies, complete loss of ATG12 in tumor cells was observed." (PMID 34904929, 2022). "We propose that the limited availability of these exogenous carbon sources in the tumor microenvironment results in killing of ATG12-deficient cells during hypoxia, resulting in low tumor hypoxia and improved outcome after therapy." (PMID 34904929, 2022). "The reduction in the absolute number of hypoxic cells within the tumor, despite reduced perfusion, suggests that ATG12 deficiency results in decreased hypoxia tolerance of cells." (PMID 34904929, 2022). "Due to ATG12 deficiency, mitochondrial biogenesis and cell bioenergetics are reduced, leading to tumor cell death." (PMID 35719323, 2022). "In vivo, ATG12 targeting resulted in decreased hypoxia tolerance, increased necrosis and sensitivity of the tumor to therapy, but in vitro ATG12-deficient cells displayed enhanced survival in nutrient-rich culture medium." (PMID 34904929, 2022). "Nevertheless, this was associated with a dramatic increase in tumor necrosis in ATG12-deficient tumors and indicates reduced hypoxia tolerance of ATG12-deficient cells." (PMID 34904929, 2022). "The selective knockout of Atg12 was associated with a strong decrease of tumor cell burden when compared with vehicle treatment, as indicated by the reduced percentage of human leukemic cells (hCD45 + ) in murine bone marrow and the spleen." (PMID 31311917, 2019). "In the univariate analysis, surgery palliative care, histopathological phenotype (gastric and pancreatic type), presence of lymph node metastases, higher TNM stage, tumor metastasis, and high expression of ATG12 and IRS2 were all associated with poor prognosis." (PMID 34976838, 2021). "The knockout of the autophagy-related gene ATG12 makes tumor cells more sensitive to T-cell killing in breast, colorectal, and kidney cancers and melanoma." (PMID 40641524, 2025). "Enhances radioresistance by sequestering miR-372-3p to induce ATG5/ATG12-dependent autophagy, enabling tumor cell recovery after radiotherapy." (PMID 41409273, 2025). "NORAD acts as a sponge for miR‐433‐3p, upregulating the expression of downstream target genes ATG5 and ATG12 to increase autophagic flux and improve tumour cell resistance to L‐OHP." (PMID 37837401, 2023). "We observed that pharmacological inhibition of autophagy-stimulating protein kinase ULK1 or RNA interference-mediated knockdown of autophagy mediator ATG12 significantly sensitized tumor cells to erastin treatment in 2D culture." (PMID 37658069, 2023). "The necrotic phenotype of ATG12 knockdown xenografts indicates that, in line with patient data, these tumor cells are less resistant to hypoxia." (PMID 34904929, 2022). "Once the tumors reached 150 mm3, doxycycline was administered via the drinking water to induce knockdown of ATG12, followed by tumor irradiation (10 Gy single fraction)." (PMID 34904929, 2022). "Given the independent prognostic value of hypoxia in HNSCC and the lack of tumor hypoxia in ATG12low tumors, these data suggest that ATG12 acquires its prognostic value through regulating tumor hypoxia." (PMID 34904929, 2022). "One study reported that the overexpression of lncRNA ZNNT1 can promote ATG12-dependent cell death to inhibit UM tumor cell growth and migration." (PMID 36544483, 2022). "In contrast to endogenous markers of hypoxia, which are dependent on tumor hypoxia, ATG12 expression seems to predict if a tumor has the capacity to support tumor hypoxia." (PMID 34904929, 2022). "The level of ATG12 expression within the tumor therefore seems to be a decisive characteristic in HNSCC tumorigenesis and treatment efficacy." (PMID 34904929, 2022).
tumor (continued). "Transfection assays validated the tumor-suppressing effect of miR-23b-3p and modulated the expression of both ATG12 and GLS1 in sorafenib-resistant HepG2 cells, curtailing sorafenib resistance in HCC." (PMID 36011286, 2022). "ATG12 (autophagy-related 12) is mainly involved in the formation of autophagic vesicles, and plays a vital role in tumor maintenance and treatment resistance." (PMID 35600868, 2022). "In this study, we found that treatment with taxifolin increased the expression of autophagy-related proteins including LC3B-II, Atg7, atg12, and Beclin-1 suggesting that the autophagic pathway was activated in our tumor model." (PMID 34462635, 2021). "The tumour sections of patients with high levels of PTBP3 also have high levels of ATG12 and LC3‐II." (PMID 31989778, 2020). "Invalidation of the key autophagy protein Atg12 strongly reduced tumor burden and improved survival of immunocompromised NSG mice engrafted with KITD816V TF-1 cells." (PMID 31311917, 2019). "The size of tumor derived from miR-214/ATG12-expressing SW480 cells was larger than those from miR-214-expressing SW480 cells (p < 0.05)." (PMID 29459645, 2018). "The transcript levels of LC3, ATG12, and Gabarapl1 genes involved in autophagic vacuole formation, increased 3.04-fold, 2.685-fold, and 1.820-fold in tumor tissues, respectively." (PMID 24527027, 2014). "ATG12 silencingsignificantly reduced JIMT1 tumor growth induced by subcutaneous injection in nude mice." (PMID 23307622, 2012). "The effects of the specific ATG12 gene knockdown on tumor growth wereinvestigated in vivo in a JIMT1 xenograft animal model." (PMID 23307622, 2012). "In this study, the effect of genistein on the expression of miR-27a as a tumor suppressor, miR-151 as an oncogene, and genes involved in apoptosis and autophagy, including ATG12, Beclin1, Caspase 3, and Caspase 9, in EJ138 BC cells was investigated using real-time PCR." (PMID 40718456, 2025). "ATG12, BECN1 and MAP1LC3B (Microtubule-associated proteins 1A/1B light chain 3 B) were reported to be associated with the three autophagy-related lncRNA through analysis in Tumor Immune Estimation Resource (TIMER), Oncomine and Human Protein Atlas Database." (PMID 38291202, 2024). "However, for the first time, our study highlights the significance of tumor-suppressing miR-23b-3p in modulating cytoprotective autophagy through ATG12 and glutamine addiction through GLS1 in sorafenib-resistant HCC." (PMID 36011286, 2022). "In line, the absence of tumor hypoxia in ATG12low tumors in patients suggests that ATG12-deficient cells are less resistant to hypoxia than ATG12 proficient cells." (PMID 34904929, 2022). "Therefore, statistical analysis between high and low ATG12 expression group was performed, and the result showed that ATG12 was significantly up‐regulated in tumour samples." (PMID 33837652, 2021). "For example, a recent research reported that lncRNA ZNNT1 could act as a tumor inhibitor in UM by upregulating ATG12 gene expression, indicating delicate interactions between lncRNAs and autophagy." (PMID 33868366, 2021). "Moreover, HOTAIR loss enhanced radiosensitivity through regulating miR-93/ATG12 axis in CRC cells and CRC xenograft tumor models." (PMID 32144238, 2020). "In addition, in vivo experiments demonstrated that HOTAIR knockdown potentiated IR-mediated anti-tumor effects by increasing miR-93 and cleaved caspase 3 expression, and reducing ATG12 and LC3 II expression in CRC xenograft tumors." (PMID 32144238, 2020). "To test this hypothesis, we evaluated the role of ATG12, which controls autophagosome formation, in tumor suppression." (PMID 26956429, 2016). "However, compared to the mean xenograft tumor size in both theshRNA-control and trastuzumab-treated groups, the mean tumor size of the ATG12-shRNA/JIMT1 cells wassmaller (858±121 mm3)." (PMID 23307622, 2012). "ATG12 knockdown reduces tumor growth and sensitizes trastuzumab-resistant xenografts totrastuzumab." (PMID 23307622, 2012).
tumor (continued). "Moreover, we found that cell transfection with an hsa-miR-30a-3p mimic blocks protective autophagy through ATG5, ATG12, and Beclin 1 suppression, which in turn increases cancer cell sensitivity to chemotherapeutic interventions in vitro and reduces tumor growth and muscle invasion in vivo." (PMID 35449123, 2022). "Although reduced perfusion is observed in ATG12-deficient tumors and thus a larger hypoxic fraction would be expected, immunohistochemistry of the exogenous hypoxia marker pimonidazole displayed no changes in the relative fraction of the viable tumor area." (PMID 34904929, 2022). "Cells with reduced ATG12 expression produced significantly more colonies in soft agar than control cells, similar to CDKN1A knockdown, consistent with a role of autophagy in tumor suppression." (PMID 26956429, 2016). "Inhibition of autophagy, either through 3-methyladenine treatment or knockdown of Beclin-1 or Atg12, significantly reduces the ability of human embryonic kidney cells (HEK293T) and malignant melanoma cells to present model antigen OVA or endogenous tumor antigens." (PMID 40248706, 2025). "Together, our data indicate that ATG12 negative tumors either are devoid of tumor hypoxia due to lowered intrinsic hypoxia-resistance." (PMID 34904929, 2022). "In this cohort, we observed that expression of ATG12 (or absence) is tumor dependent, applies to the whole tumor and not restricted to hypoxic regions only." (PMID 34904929, 2022). "The prognostic value of ATG12 was independent of other covariates such as sex, age, histological site, tumor stage and treatment type." (PMID 34904929, 2022). "This is further supported by the fact that in ATG12high tumors, ATG12 is expressed throughout the tumor and is not restricted to hypoxic areas only." (PMID 34904929, 2022). "Several ATG proteins, as well as their corresponding core complexes, such as LC3 ubiquitin-like binding system, ATG9A transport system, ATG12, autophagy-specific class III PI3K complex, and ULK 1/2 kinase core complex, are the key regulatory factors of tumor occurrence and progression." (PMID 35677537, 2022). "Gastric/pancreatic type, high expression of ATG12, lymph node metastases, and margin status were negative prognosticators of survival in patients with DAs than in those with tumor anatomical location." (PMID 34976838, 2021). "Compared with normal tissues, tumor tissues showed significantly higher mRNA levels of the following key autophagy genes: ATG5, ATG7, ATG3, ATG9A, ATG9B, ATG12, AMBRA1, and NBR1." (PMID 32582551, 2020). "For instance, human protein farnesyltransferase inhibitors (FTIs), which have been successful at suppressing tumour growth in pre-clinical studies, have been shown to induce dormancy in MCF-7 cells by upregulating protein expression levels of autophagy markers such as the Atg12 and Atg5 conjugate." (PMID 35563661, 2022). "Finally, treatment with rapamycin induced LC3-II, ATG7, ATG12 and Bcl2 expression and reduced the levels of SQSTM1/p62 and Bax, indicating that autophagy can protect tumour cells from the negative effects of HMGA2 knockdown." (PMID 31053152, 2019). "Furthermore, HULC overexpression in vivo induced tumor formation, and reduced ATG7, LC3 expression, while inducing SQSTM1 expression; however, we found that HULC overexpression did not influence ATG5, ATG12, Beclin-1, VPS34, P150 or UVRAG expression." (PMID 29022892, 2017).